TLR9 (toll like receptor 9)
Diseases named in the same sentence as TLR9 in open-access papers (continued):
Sharing a sentence is not in itself a finding about the gene and the disease.
COVID-19 (continued). "The TLR9 COVID-19 hypothesis proposes to investigate increased levels of mtDNA and ssDN as biomarkers for COVID-19 vulnerability." (PMID 33519463, 2020). "Additionally, in this current manuscript it is proposed for the first time that TLR9 could be considered as a target of “inhibition” aimed to dampen hyperinflammation and thrombotic complications in vulnerable patients that are at risk of developing late stages of COVID-19." (PMID 33519463, 2020). "It would also be recommended to evaluate the effect of TLR9 antagonists in combination with Remdesivir or other investigational antivirals on recovery time and mortality rates in adults that are hospitalized with COVID-19." (PMID 33519463, 2020). "From this viewpoint, The specific blocking the TLR9 pathway in vulnerable critically ill COVID-19 patients, might even be a more targeted approach with potentially less side effects than investigational broad-spectrum (hydroxy)chloroquine." (PMID 33519463, 2020). "If the TLR9 COVID-19 hypothesis can be further justified, well-controlled clinical trials to study safety and efficacy of TLR9 modulating drug leads for treatment and/or prevention of disease caused by a coronavirus are warranted." (PMID 33519463, 2020). "Prior art that covers safety profiles, dosing, pharmacokinetics, pharmacodynamics could help the repurposing of drug-leads and speed up the drug development process of TLR9 targeting drug candidates for COVID-19." (PMID 33519463, 2020). "The TLR9 COVID-19 hypothesis describes a mechanism of action that could explain a wide spectrum of manifestations observed in patients with severe COVID-19." (PMID 33519463, 2020). "Based on the TLR9 COVID-19 hypothesis, it is proposed that TLR9 mediated combat against COVID-19, as an accompanying effect could result in the sequestration of eosinophils." (PMID 33519463, 2020). "Based on the TLR9 COVID-19 hypothesis it is proposed that TLR9 could also play a role in the observed muscle weakness in COVID-19 patients." (PMID 33519463, 2020). "The introduced hypothesis proposes biomarkers for identification of vulnerable individuals and positions TLR9 as a promising multifaceted intervention target for prevention and/or treatment of COVID-19." (PMID 33519463, 2020). "Positioning TLR9 in COVID-19 pathology, could explain multi-organ complications and aligns with the fact that only a relatively small proportion of patients infected with SARS-CoV-2 develop severe symptoms requiring ICU." (PMID 33519463, 2020). "Here in the current investigation, we attempted to measure the mRNA expression levels of TLR3, TLR7, TLR8, and TLR9 in the nasopharyngeal epithelial cells from COVID-19 patients in order to determine the role of these innate immune system molecules in the inflammatory settings of COVID-19 patients." (PMID 35538443, 2022). "The readily availability of TLR9 modulating drug candidates that have reached clinical testing for other disorders could favor a fast track development scenario, an important advantage under the current high unmet medical need circumstances regarding COVID-19." (PMID 33519463, 2020). "CpG-55.2, another TLR9 agonist, and imidazoquinolin, a TLR7/8 agonist, have also been formulated as adjuvants in EUA COVID-19 vaccines." (PMID 40495154, 2025). "CpG-1018, a TLR9 agonist absorbed onto aluminum salt, is included in an FDA-approved HBV vaccine and has also been used in emergency use authorized (EUA) COVID-19 vaccines to boost immune responses against viral infections." (PMID 40495154, 2025). "Only one, very limited, study of AM in severe COVID-19 appears to have been carried out so far, which found activation of TLR4 and TLR9, suggesting both bacterial and viral triggers." (PMID 36769320, 2023). "Here, we observed that, at admission, COVID-19 patients had a low response to the agonist of TLR2, TLR4, TLR7/8, and TLR9, suggesting a TLR cross-tolerance." (PMID 37189696, 2023).
COVID-19 (continued). "Bruce Sullenger’s lab at Duke University discovered that the plasma and endotracheal aspirate of COVID-19 ICU patients activated various TLRs, including TLR9." (PMID 38439942, 2023). "As would be expected from the SARS-CoV-2 viral activation pattern just described, TLR3, TLR7, TLR8, TLR9, NLRP3, RIG-1 and MDA-5 are activated in patients with severe COVID-19." (PMID 36769320, 2023). "In this study, we tested an intranasal mucosal vaccine candidate for COVID-19 that consisted of a cationic liposome containing a trimeric SARS-CoV-2 spike protein and CpG-ODNs, a Toll-like receptor 9 agonist, as an adjuvant." (PMID 38006064, 2023). "Ethnicity disparity in COVID-19 mortality rates were suggested to be explained in part by elevated gene expression of TLR7 and TLR9." (PMID 35956081, 2022). "We observed that TLR7, together with MAVS, TLR9, IRF7, was downregulated in pDCs in the COVID-19 groups but more so in the groups with severe disease." (PMID 36439166, 2022). "For example, in severe COVID-19, TLR7 (viral) and TLR4 (bacterial/fungal) synergize, TLR9 and TLR4 (both bacterial/fungal) synergize and TLR2 and TLR4 (both bacterial/fungal) synergize with NLRP3 (viral and bacterial)." (PMID 33672738, 2021). "Compared to TLR7 and TLR9, a dramatically elevated level of TLR8 was shown in neutrophils after treatment with COVID-19 patient–derived EVs (MFI, 92.97 ± 25.07 versus 24.48 ± 5.03, P < 0.005), and this effect was suppressed in the presence of the TLR8 specific inhibitor Cu-CPT9a." (PMID 37904132, 2023). "In this report, we demonstrate that COVID-19 plasma exosomes stimulate protein expression of TLR3 as well as TLR7 and TLR9 in CD4+ T cells, CD8+ T cells, and CD14+ monocytes compared with cells that remained untreated, treated with plasma exosomes from non-COVID-19 or healthy donors, or poly(I:C)." (PMID 36526691, 2022). "There was no significant upregulation of TLR3, TLR7, TLR8, and TLR9 in the epithelial cells from COVID-19-Group C compared to Control-Group I, Control-Group II, and Control-Group III." (PMID 35538443, 2022). "In the current investigation, we determined the expression levels of TLR3, TLR7, TLR8, and TLR9 in the epithelial cells obtained from confirmed COVID-19 cases with and without different clinical symptoms." (PMID 35538443, 2022). "Zheng and colleagues reanalyzed the expression of MyD88 and TLRs in patients with different severity grades of COVID-19 using a public dataset and found that the expression of MyD88, TLR1, TLR2, TLR4, TLR5, TLR8, and TLR9 was increased in patients with severe to critical illness." (PMID 34834939, 2021). "Therefore, the elucidation of the interactions of SARS-CoV-2 with TLR9 axis will not only provide pivotal insights into SARS-CoV-2 infection and pathogenesis but also improve the treatment against COVID-19." (PMID 36303774, 2021). "Via the TLR9 pathways, a plethora of inflammatory mediators and cell types can be triggered such as interleukin-6 (IL-6) and tumor necrosis factor (TNF)-α in severely ill patients with COVID-19." (PMID 36303774, 2021). "Unlike mtDNA, circulating nDNA is generally not considered a DAMP, although one prior study in COVID-19 suggested nDNA could contribute to inflammation via TLR9, similarly to mtDNA." (PMID 38573766, 2024). "Therefore, suitable TLR adjuvants, such as TLR5 adjuvant flagellin or TLR9 adjuvant CpG, could be incorporated into the genome of the novel MVA-based COVID-19 vaccine candidates." (PMID 37854858, 2023). "In conclusion, low secretion of IL-8 was observed upon stimulation with TLR2, TLR4, TLR7/8, TLR9, and NOD2 agonists by the blood cells of COVID-19 patients at hospital admission and was restored after two weeks of hospitalization, which may be a contributing factor to immunosuppression." (PMID 37189696, 2023).
COVID-19 (continued). "The COVID-19 patient–derived EVs-induced NETs formation was suppressed completely in the presence of the vacuolar type H+-ATPase inhibitor bafilomycin A1 (BafA1, 100 nM), suggesting that endolysosomal TLRs such as TLR3, TLR7, TLR8 and TLR9 mediate NETs formation." (PMID 37904132, 2023). "In addition, COVID-19 plasma exosomes stimulated expression of TLR3, TLR7, TLR8, and TLR9 by PBMC." (PMID 36526691, 2022). "Based on the TLR9-COVID-19 hypothesis it is speculated that if SARS-CoV-2 and/or viral RNA could indeed translocate and accumulate in the CNS it may provoke localized immune responses via TLR9 potentially controllable via TLR9 immune modulators." (PMID 33519463, 2020). "The activation of TLR9 is notable for the fact that SARS-CoV-2 itself has not been shown to activate TLR9 but adenoviruses do, suggesting that some severe COVID-19 patients may be co-infected with adeno- or other viruses in addition to SARS-CoV-2." (PMID 36769320, 2023). "MicroBeads selected CD4+ T cells, CD8+ T cells, and CD14+ monocytes from PBMCs were treated with plasma exosomes from early-stage COVID-19 patients and non-COVID donors for 16 h at 37 °C, followed by flow cytometry for expression of TLR3, TLR7, TLR8, and TLR9 gating on live cells." (PMID 36526691, 2022). "TLR1, TLR4, TLR5, TLR8, and TLR9 expression levels were also significantly elevated in severe and critical COVID-19 patients; however, TLR3 expression was not correlated with the development of COVID-19, and an increased expression of TLR7 was observed only in patients with moderate COVID-19." (PMID 34835108, 2021).
psoriasis (47 papers, 2009 to 2026). An autoimmune condition characterized by red, well-delineated plaques with silvery scales that are usually on the extensor surfaces and scalp. "A previous RNA-seq analysis of whole blood from psoriasis patients implicated the pDC-mediated release of IFN-α after induction by IL-36 in a TLR-9-dependent manner, evidenced by the upregulation of PLSCR1 in pDCs." (PMID 35563374, 2022). "A study conducted on 175 patients with psoriasis and 170 healthy controls found that genotype and allele frequencies for Arg753Gln TLR2 and -1237 T/C TLR9 gene polymorphisms in patients with psoriasis were similar to those in healthy controls." (PMID 34790055, 2021). "The TLR9 rs352139 (T > C, A, G) polymorphism has been associated with the response to treatment with biological therapy in patients diagnosed with psoriasis." (PMID 33921427, 2021). "In a phase 2 clinical trial in patients with moderate to severe psoriasis, immune modulatory oligonucleotide- (IMO-) 3100, an antagonist of TLR7 and TLR9, was associated with a reduction in Psoriasis Area Severity Index (PASI) score." (PMID 28894754, 2017). "Reports on TLR9 suggested a pathogenic role for TLR9 in psoriasis, lupus nephritis, adjuvant-induced arthritis, and a mouse model of multiple sclerosis." (PMID 23151919, 2012). "As RPMs also express TLR9, they might contribute to the systemic inflammation associated with psoriasis." (PMID 36901755, 2023). "Previous studies have shown that HCV may cause psoriasis through upregulation of antimicrobial peptides Toll-like receptor 9 (TLR9) and interferon, which are involved in the development of psoriasis." (PMID 34215260, 2021). "Furthermore, THSP was recently proposed as a less toxic alternative to bortezomib for topical treatment for Psoriasis-like inflammation caused by TLR9 through, in particular, the attenuation of proteasomal degradation." (PMID 31061434, 2019). "Clinical trials have demonstrated the emerging benefits of using TLR9 antagonists for suppressing inflammatory pathways in psoriasis pathogenesis." (PMID 39337637, 2024). "Nevertheless, TLR9 is linked to autoimmune and autoinflammatory disorders including SLE and psoriasis, and it has been demonstrated that mammalian DNA can stimulate TLR9 when present in immune complexes." (PMID 39704565, 2024). "For example, the LL37 peptide forms a complex with nucleic acids that can activate TLR9 in KCs or plasmacytoid DCs to further promote the production of proinflammatory mediators during psoriasis." (PMID 39352743, 2024). "In psoriasis patients, LL-37 can form complexes with extracellular self-DNA and promote inflammation by activating TLR9 response in plasmacytoid dendritic cells (pDCs)." (PMID 37374090, 2023). "The antimicrobial peptide, LL-37, has been implicated in the breaking of tolerance in psoriasis and SLE through the formation of complexes with self-DNAs which activate pDCs through TLR9 with increased retention in early endocytic compartments." (PMID 37020542, 2023). "TST is a potent TLR9 inhibitor able to reduce the excessive skin inflammation in a psoriasis mouse model." (PMID 37662481, 2023). "In conclusion, we have identified an IL-36/TLR-9 axis which upregulates systemic IFN-I production in psoriasis." (PMID 31539532, 2020). "HCV infection upregulates cathelicidin, TLR9, and IFN-γ expression, which increases the susceptibility to develop psoriasis." (PMID 32927756, 2020). "The pathogenic effects of NETs in psoriasis and SLE have been attributed to their stimulatory activity on pDCs, wherein nucleic acid-mediated TLR9/7 stimulation causes type I IFN secretion, which in turn potentiates the autoinflammatory loop." (PMID 31354738, 2019). "The studies that have looked at the role of NETs in psoriasis have been limited to plasmacytoid DCs (pDCs), demonstrating that NETs, through sensing of NETs derived DNA by TLR9, promote production of type I interferons to initiate inflammation in psoriasis." (PMID 31024570, 2019).
psoriasis (continued). "For example, psoriasis, type 1 diabetes, and nonalcoholic steatohepatitis are suggested as TLR9-related diseases." (PMID 29997629, 2018). "For example, increased expression of TLRs has been observed in peripheral B cells from patients with inflammatory bowel disease, while recognition of self-DNA complexes by TLR9 mediates pDC activation in psoriasis." (PMID 28744288, 2017). "For example, recognition of self-DNA/protein complexes by TLR9 mediates pDC activation in psoriasis, breaking self-immune tolerance." (PMID 28744288, 2017). "Psoriasis-relevant IFNα production by pDCs is induced via TLR9 activation." (PMID 36901755, 2023). "A previous study demonstrated that TLR9 was also involved in psoriasis pathogenesis." (PMID 34936223, 2022). "However, the patients with late onset psoriasis were more likely to carry allele G in the Arg753Gln TLR2 polymorphism, whereas allele T in the -1237 T/C TLR9 polymorphism was statistically more frequent in the patients with early onset psoriasis." (PMID 34790055, 2021). "In conclusion, elevated expression levels of TLR1, TLR2, TLR4, TLR7, and TLR9 may facilitate the occurrence of psoriasis." (PMID 34790055, 2021). "For diseases where LL-37 may activate TLR7 and TLR9 signaling, such as psoriasis and SLE, an antagonist drug of LL-37 may provide a novel therapeutic strategy." (PMID 32927756, 2020). "Similarly to lesional skin of psoriasis, anionic self-DNA is found complexed to LL-37, and these complexes are able to trigger TLR9-mediated type I IFNs production in pDCs in CLE." (PMID 32927756, 2020). "As TLR9 is suggested to drive inflammation in NASH, anti-TLR9 mAb may be promising for therapeutic intervention in NASH or other diseases such as psoriasis, rheumatoid arthritis, and type 1 diabetes." (PMID 29988708, 2018). "In psoriasis, damaged keratinocytes release antimicrobial peptides such as β-defensins and LL-37 in the initiation phase, resulting in the formation of LL-37–DNA complexes that further amplify Toll-like receptor 9 signaling to activate plasmacytoid dendritic cells (pDCs)." (PMID 40920623, 2025). "In patients with psoriasis, elevated levels of hBD2 and LL-37 have been observed in the skin, which may contribute to chronic inflammation and propagate inflammation through the TLR9-IFN connection." (PMID 38256625, 2024). "This could be explained by the increased cutaneous levels of cathelicidin, TLR9, and IFNc of HCV-positive psoriatic patients in comparison to HCV-negative psoriatics, suggesting that HCV infection may predispose patients to developing psoriasis." (PMID 35203438, 2022). "HCV induces the production of inflammatory cytokines such as cathelicidin, TLR9, IFNγ, TNF-α, and IL-6, all of which are key contributors to psoriasis pathogenesis." (PMID 40724556, 2025). "In psoriasis, self-DNA forms a complex with LL-37 and activates pDCs via TLR9 and releases IFN-α which triggers the development of psoriasis." (PMID 37374090, 2023). "The results showed that the Psoriasis Area Severity Index score was decreased in psoriasis patients treated with immune modulatory oligonucleotide- (IMO-) 3100, an antagonist of TLR7 and TLR9." (PMID 35619184, 2022). "TLR9-expressing positive inflammatory cell counts were higher in skin lesions from patients with AOSD than those in the HC, eczema, and psoriasis groups." (PMID 35715478, 2022). "In particular, increased expression of TLR9 was observed in the skin lesions of patients with AOSD compared to that of HCs, eczema, and psoriasis groups." (PMID 35715478, 2022). "TLR9-expressing positive inflammatory cell counts were higher in skin lesions from patients with AOSD than in HC, eczema, and psoriasis groups." (PMID 35715478, 2022). "Real-time polymerase chain reaction (PCR) revealed that the expression levels of TLR3, TLR5, TLR6, TLR7, TLR9, and TLR10 in lesional skin were higher than those in peripheral blood mononuclear cells (PBMCs) of the same patients with psoriasis." (PMID 34790055, 2021).
psoriasis (continued). "TLR-8 and TLR-9 antagonists, tested in an IL23 psoriasis mouse model, inhibited the Th1 and Th17 responses, and were active against psoriasis in a proof-of-concept trial." (PMID 28095445, 2017). "IMO-3100 is a novel DNA-based antagonist of TLR7 and TLR9 for the treatment of SLE, RA, multiple sclerosis, psoriasis, and colitis." (PMID 23151919, 2012). "We considered the antimicrobial peptide LL-37 as a potential candidate based on a recent report that LL-37 isolated from psoriasis skin lesions can bind DNA and trigger peripheral blood pDC to secrete IFN-α via TLR-9." (PMID 21904619, 2011). "Recent publications demonstrated that the anti-microbial peptide LL-37 isolated from psoriasis skin lesions can bind eukaryotic DNA and RNA and trigger peripheral blood pDC to secrete IFN-α in a TLR-9 dependent manner." (PMID 21904619, 2011). "Recent studies have found that certain factors regulate the AIM2 inflammasome signaling pathway and participate in the pathogenesis of psoriasis, including prokineticin 2 (PK2), caspase recruitment domain family member 18 (CARD18), aurora kinase A (AURKA), TLR-7, TLR-8, and TLR-9 antagonists." (PMID 36118867, 2022). "Furthermore, the percentage of inflammatory cells expressing TLR9 in skin lesions from patients with AOSD was significantly greater than that in HC (p = 0.001) and patients with eczema (p = 0.041) or psoriasis (p = 0.001)." (PMID 35715478, 2022). "Psoriasis is a chronic inflammatory autoimmune disease that can be initiated by excessive activation of endosomal toll-like receptors (TLRs), particularly TLR7, TLR8, and TLR9." (PMID 28894754, 2017). "In the case of psoriasis, the endogenous antimicrobial peptide LL37 forms a complex with self-DNA that is delivered to and retained within early endocytic compartments of pDCs to trigger TLR9 and to induce IFNα production." (PMID 19563672, 2009). "This has given rise to the notion that under certain conditions, e.g., in psoriasis patients, tolerance to self-DNA and -RNA can be ‘accidentally’ broken by LL37 involving the nucleic acid-sensing Toll-like receptor (TLR) 7, TLR8 (ssRNA) and TLR9 (DNA) in humans, and Tlr7, Tlr13 and Tlr9 in mice." (PMID 38783164, 2024). "In this imiquimod-induced psoriasis model, TLR7 and TLR9, but not TLR7 or TLR9 alone, are required for its pathogenesis, suggesting DNA recognition is important for the development of disease." (PMID 33633744, 2020).